CTNND1 (catenin delta 1)
Diseases named in the same sentence as CTNND1 in open-access papers (continued):
Sharing a sentence is not in itself a finding about the gene and the disease.
tumor (continued). "We binarized tumor cells based on whether the expression of CTNND1 was greater than 0, and compared the proportion of positive and negative cell rates in tumor and non-tumor cells." (PMID 38169514, 2024). "In addition, cell-cell communication analysis revealed that CTNND1+ tumor cells communicated with immune subpopulations frequently." (PMID 38169514, 2024). "The tumor driver CTNND1 is the key component involved in cell–cell adhesion and Rac1, Cdc42, and Ras homolog gene family member A (RhoA) activation and has been reported to repress the migration and invasion of tumor cells." (PMID 39338204, 2024). "Finally, we explored the relationship between the expression of CTNND1 and the tumor immune microenvironment as well as immune regulatory biological processes." (PMID 38169514, 2024). "In addition, compared with CTNND1- tumor cells, CTNND1+ tumor cells showed the highest cell-cell communication strength with stromal cells (fibroblasts and endothelial cells), and presented significantly more specific interactions with stromal cells." (PMID 38169514, 2024). "Next, we intersected immunotherapy-associated differential genes with anoikis-related genes, and the genes significantly expressed in tumor cells, obtaining a special biomarker: CTNND1, which can be inferred as an immunotherapy and tumor anoikis related biomarker." (PMID 38169514, 2024). "Mechanistically, downregulation of catenin delta 1 (CTNND1) in metastatic bone lesions promoted tumor recruitment to bone by upregulating CXCL12/CXCR4 axis via PI3K/AKT/HIF-1α pathway, while recruitment of neutrophils in the bone was stimulated by secretion of GM-CSF and IL-8." (PMID 35994202, 2022). "Also, miR-425-5p stimulated tumor growth and metastasis via CTNND1-mediated β-catenin signaling activation and EMT mechanisms in colorectal cancer." (PMID 34852711, 2022). "With the development of DNA-microarray and liquid biopsy detection, CTNND1 might be a promising gene biomarker if it could be dynamically monitored at the circulating tumor DNA level, which promoted CTNND1 to be detected conveniently in clinics." (PMID 34830862, 2021). "When recruited to the bone, tumor cells with CTNND1 reduction exhibit a stronger ability to survive by secreting more GM-CSF and IL-8, which contributed to the infiltration of immature myeloid cells, especially neutrophils, impairing proliferation and cytotoxicity of CTLs." (PMID 34830862, 2021). "In BC, high expression of CTNND1 is required for tumor growth and metastasis." (PMID 31913290, 2020). "Furthermore, qRT-PCR results suggested that the levels of KCNQ1OT1 and CTNND1 were declined in tumor tissues from the sh-KCNQ1OT1 group versus the sh-con group, while the miR-329-3p level was increased." (PMID 32760218, 2020). "CTNND1 is deregulated in the majority of human cancers and could act as either a tumor suppressor or an oncogene depending on its subcellular localization." (PMID 29228664, 2017). "Of interest, CTNND1 is a multifaceted intracellular signaling protein, which may function as either a tumor suppressor or a metastasis promoter depending on its subcellular localization and E-cadherin expression status." (PMID 29228664, 2017). "When expressed in cell membrane, CTNND1 functions as a tumor suppressor by stabilizing E-cadherin." (PMID 29228664, 2017). "Alteration of CTNND1 localization was observed to promote tumor progression in human breast cancer." (PMID 28931919, 2017). "In this context, a core function of CTNND1 in mammalian cells is to stabilize E-cadherin at cell membrane by preventing its endocytosis and degradation in the lysosome, thus facilitating E-cadherin-mediated suppression of tumor invasion and metastasis." (PMID 29228664, 2017). "An in-vivo assay showed that CTNND1 dramatically promoted HCC cell tumor formation and metastasis." (PMID 27193094, 2016).
tumor (continued). "Our study provides evidence that CTNND1 functions as a novel tumor oncogene in HCC, and may be a potential therapeutic target for HCC management." (PMID 27193094, 2016). "Reduction of ESRP1 in tumor cells was evaluated by immunohistochemistry, associated with microsatellite stability and switch to mesenchymal splice signatures of FGFRs, CD44, ENAH and CTNND1(p120-catenin)." (PMID 27650542, 2016). "We demonstrated with the studied patient cohort and the conditional cell model that expression of ESRP1 in CRC tumor cells is associated with a shift in EMT splicing patterns of ENAH and CTNND1 (p120-catenin), thus confirming a key role of ESRPs in CRC progression." (PMID 27650542, 2016). "Thus, CTNND1 may function as an oncogene in various tumor types (including EC) by regulating several signaling pathways, such as the Wnt pathway." (PMID 37345024, 2023). "Besides, KCNQ1OT1 knockdown inhibited CRC tumor growth through the miR-329-3p/CTNND1 axis in vivo." (PMID 32760218, 2020). "Thus, miRNA‐143‐3p may act as a tumor suppressor by negatively regulating CTNND1, which is considered an oncogene." (PMID 32592277, 2020). "Then, we calculated the tumor purity and immune infiltration score in each sample through ESTIMATE, and carried out correlation analysis with the expression of CTNND1." (PMID 38169514, 2024). "ESRP1 participates in AS of important transcripts, such as FGFR2, CD44, p120-Catenin (CTNND1), and hMena (ENAH) in regulating the process of EMT involved in tumor metastasis." (PMID 33495408, 2021). "Our study demonstrated that circMAST1 functions as a tumor promoter and induces HCC cancer cell proliferation and invasion through the miR-1299/CTNND1 axis, suggesting that circMAST1 is a potential biomarker and therapeutic target for HCC." (PMID 32393764, 2020). "Whole genome sequencing (WGS) analysis of a tumor expressing the CTNND1-ARHGAP26 fusion revealed that g.chr11:57,578,103 (CTNND1 intron 15) was aberrantly fused to g.chr5:142,358,707 (ARHGAP26 intron 11) at the genomic DNA level." (PMID 30361512, 2018). "As exemplified by the detailed analysis of CTNND1 and PRICKLE1, these isoform switching events potentially provide new insights into the post-transcriptional regulatory mechanisms of tumor subtypes and cancer biology." (PMID 26939613, 2016). "We identified three tumor suppressor miRNAs (miR-34a, miR-124, and miR-1271) that target three adhesion molecules (L1 Cell Adhesion Molecule (L1CAM), Integrin Subunit Beta 3 (ITGB3), Catenin Delta 1 (CTNND1))." (PMID 34298609, 2021). "As the CXCR4/CXCL12 axis was well known for chemotaxis of tumor cells in bone metastasis, we co-cultured TNBC cell lines with reduced CTNND1 together with fibroblasts, osteoblasts and CXCL12 cytokine, respectively, as CXCL12 was mainly produced by fibroblasts and osteoblasts in bone." (PMID 34830862, 2021). "It has been shown that ESRP1/2 activation leads to oncogenic activation of several ESRP1/2 target genes such as MAP 3 K7, mTOR, GSK3ß, RB1, CTNND1, E-Cadherin, and CD44, which drive tumor cell proliferation and EMT, key features of advanced and aggressive cancers." (PMID 33339518, 2020). "Proteomic and biochemical analyses further demonstrated that wild-type MORC2, but not PRD deletion mutant, interacted with catenin delta 1 (CTNND1), a cadherin-associated protein that participates in tumor invasion and metastasis." (PMID 29228664, 2017). "Data suggested that after CTNND1 highly expressed, the SW480 and LS1034 cells proliferation rate (P < 0.05), migratory and invasive ability were increased (P < 0.05), however, apoptosis ability was hindered (P < 0.05).These results indicate that CTNND1 may work as a tumor promoter in CRC cells." (PMID 32760218, 2020).
cancer (58 papers, 2009 to 2025). A tumor composed of atypical neoplastic, often pleomorphic cells that invade other tissues. "The recurrent missense mutation R439C in CTNND1 has been identified as a novel putative cancer driver variant for NB." (PMID 39338204, 2024). "β-catenin (encoded by CTNNB1) and p120 catenin (p120Cat; a δ-catenin encoded by CTNND1) have been linked to cancer growth, EMT and metastasis, and their tyrosine phosphorylation is thought to be oncogenic." (PMID 38904097, 2024). "Genomic alterations of p120-catenin (encoded by CTNND1) are relatively rare in human cancer (cBioPortal)." (PMID 37255594, 2023). "Previous work has shown miR-298’s role in targeting proteins implicated in cancer, such as catenin delta 1, apoptotic protein Bax, and polycomb protein enhancer of zeste." (PMID 31942037, 2021). "A large amount of recent data has implicated CTNND1 in the regulation of cancer development and progression, and previous studies have demonstrated that CTNND1 plays a functional role in HCC cell proliferation, migration, invasion, and metastasis." (PMID 32393764, 2020). "Cytosolic CTNND1 drives E-cadherin-deficient cancer cell migration, invasion and metastasis through activation of Rho-family GTPases Rac1 and Cdc42 and inhibition of RhoA activity." (PMID 29228664, 2017). "Recently, a large amount of data has implicated CTNND1 in the regulation of cancer development and progression." (PMID 27193094, 2016). "Interestingly, S268 phosphorylation in CTNND1 has been implicated in mesenchymal–epithelial transition in cancer cells via protein kinase C." (PMID 39601342, 2024). "Indeed, elevated levels of CTNND1 in the nucleus have been observed in E-cadherin-deficient cancer cells, indicating a potential role for nuclear CTNND1 in enhancing the metastatic phenotype associated with E-cadherin downregulation." (PMID 29228664, 2017). "Moreover, CTNND1 had been implicated in the metastasis and pathogenesis of several human cancers." (PMID 19835603, 2009). "Using the Cancer Genome Interpreter, we identified five recurrent cancer driver mutations spanning MUC16, MUC4, ALK, and CTNND1, with the latter being novel and containing a missense mutation, R439C." (PMID 39338204, 2024). "There is a large amount of research focusing on the role of CTNND1 in cancer development and progression; however, in PCa, it is still not well-elucidated." (PMID 37218885, 2023). "Increased CDH3 expression also increases cell motility and migration in cancer by interfering with CTNND1 and CDH1." (PMID 37151391, 2023). "Recently, increasing studies reported that CTNND1 functioned as an oncogene during cancer occurrence and development." (PMID 34852711, 2022). "Other interesting candidates previously related to cancer include CTNND1 and TPM2, for which alternative splicing events in both transcripts have been correlated with cancer, and HAUS3." (PMID 34496885, 2021). "Combined with Kyoto Encyclopedia of Genes and Genomes (KEGG) database pathway analyses, PI3K/AKT pathway was found to be activated in both cancer cell lines when their CTNND1 were knocked down." (PMID 34830862, 2021). "Reduction of CTNND1 promotes bone metastasis of TNBC cells by facilitating homing cancer cells to bone and the survival of the metastatic cells via upregulating CXCR4/CXCL12 axis and neutrophils Infiltration in bone." (PMID 34830862, 2021). "Mechanistically, miR-96-5p prevents cancer metastasis by targeting CTNND1-mediated Wnt/β-catenin signaling in BCa." (PMID 31913290, 2020). "The research clarifies circMAST1 function as a sponge of miR-1299 to promote CTNND1-induced HCC cancer cell proliferation and invasion." (PMID 32393764, 2020). "It has been shown that CTNND1 regulates Wnt/β-catenin signaling through its direct interaction with the transcriptional repressor Kaiso in other cancers." (PMID 27193094, 2016).
cancer (continued). "The putative role of CTNND1 as an oncogene in cancer development is supported by the observations that CTNND1 is highly expressed in some tumors relative to normal tissues." (PMID 27193094, 2016). "We found that CTNND1 expression was significantly up-regulated in cancer lesions compared with paired normal liver tissues." (PMID 27193094, 2016). "In clinical HCC samples, we found that CTNND1 expression was significantly up-regulated in cancer lesions compared with paired normal liver tissues." (PMID 27193094, 2016). "The mRNA of CXCR4 was prominently upregulated in cancer cells with CTNND1 knockdown, suggesting that it might be regulated at the transcription level." (PMID 34830862, 2021). "In clinical HCC samples, CTNND1 (δ-catenin) expression was found to be up-regulated significantly in cancer tissues compared with paired normal liver tissues, and overexpression of CTNND1 in HCC cell lines promotes carcinous characters through indirectly enhancing Wnt/β-catenin signaling." (PMID 29977206, 2018). "Thus, CTNND1 promotes characteristics of migration that have been proposed as a model for cancer progression and metastasis." (PMID 27193094, 2016). "In addition to FGFRs, TGF-β induces alternative splicing of CD44, Mena, and CTNND1 (also known as δ-catenin or p120 catenin), which are reportedly involved in cancer progression." (PMID 22111550, 2012). "Some of the prominent genes we identified through the networks are DOK5, APP, CTNND1, STX6, STX10, STX16, BACE1, and BACE2; which, agree with the regulation of various cancers based on their co-expression patterns in GeneMANIA." (PMID 37218885, 2023). "Five of these 25 alternatively spliced genes are well-known to play a role in cancer (ARHGEF11, CD44, CTNND1, ENAH, MBNL1)." (PMID 33845831, 2021). "Six genes, including ADD3, CTNND1, EPB41L3, F3, MUC4 and PDGFA, showed cancer-tissue-specific DES events." (PMID 22905095, 2012). "There are many AS events involves in EMT during cancer progression, such as splicing of FGFR2, CD44, CTNND1, and ENAH and they may become therapeutic points- it is therefore timely to ask ourselves: Can these AS events in EMT be targets of cancer therapy?" (PMID 38002944, 2023). "Similarly, the miR-329-3p/CTNND1 (Catenin delta-1) axis was demonstrated to interact with KCNQ1OT1 to modulate SW480 and LS1034 CRC cancer cell proliferation, migration, invasion, and apoptosis." (PMID 34827600, 2021). "For example, genes with Motif 1 in Molecular Mechanisms of Cancer pathway include MAPK1, BRAF, SMAD2, FZD5, FZD8, NOTCH1 and LRP1, whereas genes with Motif 2 and/or Motif3 in the same pathway include LRP5, LRP6, MDM2, CTNND1, SMAD3, SMAD4 and SMAD7." (PMID 26040697, 2015). "Finally, we compared the enrichment scores of various steps in the cancer immune cycle between CTNND1 high and low groups, our finding suggested a significant negative correlation between CTNND1 expression and various processes of the immune cycle." (PMID 38169514, 2024). "Hence, we postulated that disruption of CTNND1-cortactin interaction may be secondary to curcumin-induced dephosphorylation of cortactin by PTPN1 and may contribute to its effects of curcumin on cancer cell migration." (PMID 24465712, 2014).
infection (4 papers, 2017 to 2025). The state of being infected such as from the introduction of a foreign agent such as serum, vaccine, antigenic substance or organism. "This systematic approach revealed that CD81, CD44, CD98, caveolin-1 and catenin delta-1 were down-regulated during infection whereas GRP-78 was up-regulated." (PMID 29121670, 2017).
neurodevelopmental disorder (1 paper, 2020). A behavioral and cognitive disorder with onset during the developmental period that involves impaired or aberrant development of intellectual, motor, or social functions. "While further studies will be necessary to definitively understand the phenotype-genotype correlations, CTNND1, and perhaps CDH1, should be considered when patients present with characteristic craniofacial anomalies, congenital cardiac defects and neurodevelopmental disorders." (PMID 32196547, 2020).
CTNND1 also shares sentences with these, for which no sentence is quoted: prostate carcinoma (6 papers); schizophrenia (4); endometrial cancer (3); non-small cell lung carcinoma (3); Lobular Carcinoma (2); myocardial infarction (2); adenocarcinoma of the breast (1); adenoma (1); anxiety disorder (1); astrocytoma of the brain (1); autism spectrum disorder (1); B-cell acute lymphoblastic leukemia (1); Barrett esophagus (1); Blepharocheilodontic syndrome 2 (1); Branchio-oculo-facial syndrome (1); carcinosarcoma (1); cerebral infarction (1); cervical cancer (1); choanal atresia (1); colitis (1); Colon (1); coronary artery disease (1); cortical cataract (1); Crohn disease (1); Distichiasis (1); endometrioid adenocarcinoma (1); epithelial ovarian cancer (1); esophageal cancer (1); HCMV infection (1); Headache (1).
A further 27 diseases each share a sentence with CTNND1 in 1 paper.